CEP44 (centrosomal protein 44)
Description:
Centriole-enriched microtubule-binding protein involved in centriole biogenesis. In collaboration with CEP295 and POC1B, is required for the centriole-to-centrosome conversion by ensuring the formation of bona fide centriole wall. Functions as a linker component that maintains centrosome cohesion. Associates with CROCC and regulates its stability and localization to the centrosome.
Synonyms: PS1TP3; KIAA1712
Tractability: PROTAC: ubiquitination databases record sites on it.
Gene: Protein-coding gene on chromosome 4 (174,283,295 to 174,333,380, forward strand). Ensembl gene ENSG00000164118.
Subcellular location: Cytoplasm, cytoskeleton, microtubule organizing center, centrosome; Cytoplasm, cytoskeleton, microtubule organizing center, centrosome, centriole; Cytoplasm, cytoskeleton, spindle pole; Midbody
Subcellular location (Human Protein Atlas): Basal body; Cytosol
Gene Ontology:
Molecular function: microtubule binding; protein binding
Biological process: centriole replication; centriole-centriole cohesion; centrosome cycle
Cellular component: centriole; centrosome; ciliary basal body; spindle pole; midbody
Genetic constraint (gnomAD): Loss-of-function variants: 25 observed, 26.06 expected, observed/expected ratio (o/e) 0.96, 90% interval 0.7 to 1.34. The upper end of that interval is the gene's LOEUF score, 1.34, which puts it in group 5 of 6, group 1 being the genes least tolerant of losing a copy. Missense variants: 272 observed, 290.19 expected, observed/expected ratio (o/e) 0.94, 90% interval 0.85 to 1.04. Synonymous variants: 97 observed, 97.55 expected, observed/expected ratio (o/e) 0.99, 90% interval 0.84 to 1.18.
Homologues: Orthologues: chimpanzee CEP44 (93% identical), macaque CEP44 (88% identical), pig CEP44 (81% identical), dog CEP44 (73% identical), rabbit CEP44 (70% identical), rat Cep44 (69% identical), mouse Cep44 (67% identical), guinea pig CEP44 (57% identical), tropical clawed frog cep44 (45% identical), zebrafish cep44 (29% identical).
Diseases named in the same sentence as CEP44 in open-access papers:
CEP44 is named in the same sentence as 1 disease in open-access papers, as found by Europe PMC text mining. Sharing a sentence is not in itself a finding about the gene and the disease. The quoted sentences say what the papers report.
cancer (1 paper, 2019). A tumor composed of atypical neoplastic, often pleomorphic cells that invade other tissues. "CEP44 is a centrosomal protein while its role in cancers is still unclear." (PMID 30988073, 2019).